TGFBR2 (transforming growth factor beta receptor 2)
Diseases named in the same sentence as TGFBR2 in open-access papers (continued):
Sharing a sentence is not in itself a finding about the gene and the disease.
gastric cancer (continued). "We verified that TGFBR2 was a direct target of miR-17-5p, consistent with the prediction of bioinformatics tools, and that miR-17-5p could promote the proliferation and migration of gastric cancer cells by negatively regulating the expression of TGFBR2." (PMID 27120811, 2016). "TGFBR2 plays a crucial role in the carcinogenesis and malignant process of gastric cancer, but the mechanism remains unclear." (PMID 27120811, 2016). "The results of our study suggest a novel regulatory network in gastric cancer mediated by miR-17-5p and TGFBR2 and may indicate that TGFBR2 could serve as a new therapeutic target in gastric cancer." (PMID 27120811, 2016). "We next examined the biological effects of miR-17-5p and TGFBR2 on gastric cancer cells." (PMID 27120811, 2016). "As TGFBR2 mutations have not previously been functionally validated in gastric cancer, we modeled the metastatic potential of TGFBR2 loss in a murine three-dimensional primary gastric organoid culture." (PMID 25315765, 2014). "We performed cDNA microarray analysis to identify the downstream target genes of SOX2 in gastric cancer cells, and found that many tumor-associated genes exhibited significant changes in expression after SOX2-overexpression (e.g., LTF, PPP2R1B, TGFBR2, SERPINE1, MMP9, HMGA1 and SOX9)." (PMID 21304604, 2011). "Thus, TGFBR2 exhibits a cancer-suppressive function in gastric cancer, the dysregulation of which may increase the proliferation and migration of cancer cells." (PMID 27120811, 2016). "We found that DCLK1 expression significantly correlates with both TGFB1 and CXCL12 and their receptors TGFBR1, TGFBR2, and TGFBR3, and CXCR4, respectively, in colon and stomach cancer patients." (PMID 31979136, 2020). "Deep-sequencing of a primary tumor and metastasis from a single patient, and functional validation in culture, reveals that TGFBR2 and FGFR2 act as drivers of gastric cancer." (PMID 25222187, 2014). "The current study demonstrated a post-transcriptional regulation strategy for TGFBR2 and its negative cancer-promoter function in gastric cancer cells." (PMID 27120811, 2016). "The protein levels but not the mRNA levels of TGFBR2 were downregulated in gastric cancer, indicating that the expression of TGFBR2 was primarily regulated at a post-transcription level." (PMID 27120811, 2016). "In this study, we detected an inverse expression pattern of miR-17-5p and TGFBR2 in human gastric cancer and paired noncancerous tissues." (PMID 27120811, 2016). "Homozygous TGFBR2 deletion is also present in a subset of TCGA gastric cancers which are largely comprised of non-metastatic tumors." (PMID 25315765, 2014). "Additionally, miR-21-5p could inhibit TGFBR2 expression in the TGF-β signaling pathway, thereby suppressing myofibroblast differentiation, in contrast to other reports, in which miR-21-5p promoted gastric cancer and kidney fibrosis by upregulating Smad7 in the TGF-β signaling pathway." (PMID 34344478, 2021).
liver fibrosis (30 papers, 2010 to 2025). "To uncover the underlying pro-inflammatory mechanism of miR-20a-5p in liver fibrosis, we selected and verified TGFBR2, which is a key functional receptor in TGF-β signaling pathway, as a direct target gene of miR-20a-5p." (PMID 32117757, 2020). "In conclusion, hsa_circ_0009096 promoted HSC proliferation and hepatic fibrosis during BA pathogenesis by accelerating TGFBR2 expression by sponging miR-370-3p." (PMID 38766485, 2024). "To validate this, we observed a significantly decreased TGFBR2 expression in the LX-2 cells that were transfected with hsa_circ_0009096 siRNA, as well as in the cellular hepatic fibrosis model induced by TGF-β1 treatment." (PMID 38766485, 2024). "It was demonstrated that the down-regulation of miR-20a-5p in liver fibrosis resulted in TGFBR2-activated TGF-β/SMAD signaling pathway, followed by the activation of macrophage and increase in ECM deposition." (PMID 38139231, 2023). "The down-regulated miR-20a-5p and the axis miR-20a-5p/TGFBR2 are involved in inflammation during liver fibrosis." (PMID 38139231, 2023). "To reveal the pro-inflammatory mechanism of miR-20a-5p in liver fibrosis, we selected and verified TGFBR2, a key functional receptor in TGF-β signaling pathway and a target gene of miR-20a-5p." (PMID 32117757, 2020). "The downregulation of miR-20a-5p in liver fibrosis resulted in TGFBR2-activated TGF-β signaling pathway, followed by the activation of macrophage and extracellular matrix (ECM) production by hepatic stellate cell (HSC)." (PMID 32117757, 2020). "The downregulation of miR-20a-5p in liver fibrosis resulted in TGFBR2-activated TGF-β signaling pathway, followed by the activation of macrophage and extracellular matrix (ECM) production by HSC." (PMID 32117757, 2020). "Collectively, our data strongly suggests that miR-20a-5p down-regulation reinforce TGF-β signaling, at least in part, through alleviating to target TGFBR2 mRNA, leading to inflammation during liver fibrosis progression." (PMID 32117757, 2020). "Among the 28 target genes, we considered that MAPK1, TGFBR1, and TGFBR2 represent the potential target genes that could be regulated by miR-130a-3p and involved in the liver fibrosis of schistosomiasis." (PMID 34421906, 2021). "These evidences suggested that miR-130a-3p could inhibit TGF-β/Smads signaling, at least in part, via TGFBR1 and TGFBR2 to affect the activation of HSCs and the phenotype of macrophages involving the development of liver fibrosis." (PMID 34421906, 2021). "Notably, high levels of HOTTIP downregulate miR-148a, increase the expression levels of the miR-148a targets TGF-beta receptor type-1 (TGFBR1) and TGF-beta receptor type-2 (TGFBR2) and thus contribute to liver fibrosis." (PMID 32098245, 2020). "Because we demonstrated miR-20a-5p alleviated liver fibrosis may through lighten inflammation, we sought to evaluate the relevance between TGFBR2 and inflammation." (PMID 32117757, 2020). "Thus, we initially investigated the expressions of TGFBR2 in liver fibrosis samples from patients." (PMID 32117757, 2020). "In liver fibrosis, downregulation of miR-20A-5p can lead to the activation of transforming growth factor-beta (TGF-β) Induced by TGF-β receptor 2 (TGFBR2), which exacerbates inflammation." (PMID 36291136, 2022). "For example, miR-219 can modulate liver fibrosis by directly targeting tumor growth factor β receptor 2 (TGFBR2), while miR-34a-5p targets Smad4 and modulates TGF-β1/Smad3 pathway in HSCs to ameliorate liver fibrosis." (PMID 34161325, 2021). "MiR-20a-5p/TGFBR2 axis resulted in activation of TGF-β signaling pathway and regulated inflammation-driven liver fibrosis." (PMID 34249133, 2021). "TGFBR1 and TGFBR2 levels were increased by high levels of HOTTIP, which led to the progression of liver fibrosis." (PMID 34899344, 2021).
liver fibrosis (continued). "Our results identify the miR-20a-5p/TGFBR2 axis as a key regulator of TGF-β signaling, and highlight the critical role of miR-20a-5p in the development of liver fibrosis." (PMID 32117757, 2020). "The TGF-β1/smad signalling pathway can regulate liver homeostasis, although the distinct role of TGFBR2 and TGFBRAP1 in the TGF-β1/smad signalling pathway had been observed previously, playing a vital role in liver fibrosis and hepatocarcinogenesis." (PMID 31534460, 2019). "To characterize the effects of TGFBR1 and TGFBR2 on liver fibrosis, we knocked down the expression of TGFBR1 and TGFBR2 in HSC-T6 cells using siRNA transfection." (PMID 28518142, 2017). "This indicated that tumor‐secreted VGF may interact with TGFBR2 of HSCs and then activate the canonical TGF‐β‐SMAD signaling pathway to trigger liver fibrosis." (PMID 39422674, 2024). "The circRNA cVIM may act as a sponge for miR-122-5p and miR-9-5p to enhance expression of TGFBR1 and TGFBR2 and promote activation of the TGF-β/Smad pathway, thereby accelerating the progression of liver fibrosis." (PMID 38243118, 2024). "Until now, there is no study showing the role of miR-200a-3 and miR-20a-5p in liver fibrosis, besides our previous study on miR-20a-5p/TGFBR2 axis." (PMID 34235224, 2021). "Further studies revealed that cVIM, mainly expressed in the cytoplasm, may act as a sponge for miR-122-5p and miR-9-5p to enhance expression of type I TGF-β receptor (TGFBR1) and TGFBR2 and promotes activation of the TGF-β/Smad pathway, thereby accelerating the progression of liver fibrosis." (PMID 38243118, 2024). "Our results collectively suggest that cVIM acts as a sponge for miR-122-5p and miR-9-5p to enhance expression of TGFBR1 and TGFBR2, leading to the phosphorylation of Smad2 (a downstream mediator of TGF-β signaling), which finally promotes TGF-β/Smad pathway and the progression of liver fibrosis." (PMID 38243118, 2024).
prostate carcinoma (29 papers, 2003 to 2025). A carcinoma that arises from epithelial cells of the prostate gland. "Recently, we demonstrated that low expression levels of TGFBR2 mRNA are associated with more aggressive prostate cancer phenotypes and with a higher risk to develop resistance to anticancer treatment." (PMID 25909813, 2014). "Our experiments found out that hypoxia could attenuate the expression of TGFBR2, whereas the underlying mechanism and significance of this regulation in prostate cancer remain poorly understood." (PMID 29699590, 2018). "BMPs are a diverse class of growth factor proteins that belong to the transforming growth factor-β (TGFB1, TGFB2, TGFBR1, TGFBR2) superfamily, and aberrant expression of various BMPs has been reported in several tumor tissues, including prostate cancer." (PMID 40596459, 2025). "In prostate cancer research, hypoxia-induced EZH2 causes hypermethylation of the TGFBR2 promoter, reducing its expression." (PMID 40427283, 2025). "The resistance of prostate cancer cells to TGF-β-mediated growth inhibition is thus possibly a result of decreased expression of TGFBR2, which acts as a tumor suppressor gene." (PMID 31842336, 2019). "Transforming growth factor-β1 (TGF-β1) induces EMT in prostate cancer (PCa) by binding to TGF-beta receptor 2 (TGFBR2) to activate TGF-β signaling." (PMID 32010624, 2019). "Firstly, we treated the three prostate cancer cell lines with 10 μmol/L of DNA demethylation agent 5-Aza-2′-deoxycytidine (5-Aza-DC), and detected the expression level of TGFBR2 by RT-PCR." (PMID 29699590, 2018). "Our findings elucidate diverse hypoxia-regulated pathways including EZH2-mediated hypermethylation and miR-93-induced silencing contribute to attenuation of TGFBR2 expression and promote cancer progression in prostate cancer." (PMID 29699590, 2018). "As a result, methylation silencing of TGFBR2 in prostate cancers contributed at least partly the decreased expression of TGFBR2." (PMID 29699590, 2018). "Prostate cancer cell lines were cultured in hypoxia or normoxia to evaluate the effect of hypoxia on TGFBR2 expression." (PMID 29699590, 2018). "Since human prostate cancer has a primarily luminal cell phenotype, we deleted Pten and Tgfbr2 specifically in luminal cells." (PMID 29782499, 2018). "In this study, we demonstrated the impact of hypoxia on the expression of TGFBR2 in prostate cancer cells." (PMID 29699590, 2018). "Our experiments showed that hypermethylation in TGFBR2 promoter reduced the expression of TGFBR2, which was in accordance with previous findings that Tgfbr2 underwent methylation silencing in rat prostate cancers." (PMID 29699590, 2018). "Previous studies have shown that methylation silencing of TGFBR2 resulted in lower expression of TGFBR2 in rat prostate cancer." (PMID 29699590, 2018). "The first important finding of our study is that hypoxia reduces the expression of TGFBR2 in prostate cancer." (PMID 29699590, 2018). "It reported that rat prostate cancer cell lines had increased H3K4me2 or H3K9me3 at the Tgfbr2 promoter, while human prostate cancer cell lines were likely to have increased H3K27me3 at the TGFBR2 promoter." (PMID 29699590, 2018). "The expression of TGFBR2 is often found to be altered in several types of malignance, such as metastatic breast cancer, colorectal cancer, and prostate cancer." (PMID 29699590, 2018). "Human prostate cancer cells typically have a luminal phenotype, whereas in the PbCre4 model the Cre is expressed in both basal and luminal cells and deletion of Tgfbr2 appears to activate basal cell proliferation." (PMID 29782499, 2018). "The Cancer Genome Atlas (TCGA) data showed that TGFBR2 expression was significantly reduced in prostate cancer tissues." (PMID 29699590, 2018). "Studies on prostate cancer have demonstrated androgenic control in TGF-β1 signaling through suppression of TGFBR2 transcription suppression." (PMID 26091707, 2016).
prostate carcinoma (continued). "For instance, decreased TGFBR2 expression was observed in prostate cancer cells, carcinoma cells of the urinary bladder, and the oropharyngeal mucosa during SIV infection." (PMID 27378305, 2016). "Blocking PTH1R rescued TGFBR2 protein levels in osteoblasts and overcame enzalutamide resistance in a coculture system of prostate cancer and osteoblast cells, suggesting PTH1R as a novel target to overcome enzalutamide resistance in prostate cancer bone metastasis." (PMID 37046642, 2023). "Moreover, PTHrP/PTH1R was found to mediate drug resistance in prostate cancer bone metastasis, possibly through facilitating TGFβ type II receptor (TGFBR2) degradation." (PMID 37046642, 2023). "A similar approach is being tested with dominant-negative TGFBR2 CAR-T cells in prostate cancer." (PMID 35406544, 2022). "For instance, TGFBR2 down-regulation will promote the malignant progression of prostate cancer." (PMID 34900984, 2021). "Finally, a TGFBR2-based CSR, which signals through 4-1BB (TGFBR2:4-1BB), enhanced the anti-tumor function of prostate cancer targeted CAR T cells, as well as NY-ESO-1 TCR+ T cells for melanoma." (PMID 32570906, 2020). "For instance, combination of a first generation prostate cancer targeting CAR (signal 1) with a TGFBR2:4-1BB CSR (signal 2) and a IL-4/7R CCR (signal 3) has produced promising results in a mouse model of pancreatic cancer, by splitting engineered T cell signals in a TME specific manner." (PMID 32570906, 2020). "Finally, using RNA-seq to probe the in vivo rat prostate cancer system, digitoxin was found to suppress Nfkb signaling to multiple mRNAs, including Tgfbr2, as well as multiple EMT mRNAs." (PMID 31428571, 2019). "TGF-β and AR synergistically stimulate apoptosis in prostate cancer cells overexpressing TGFBR2." (PMID 31842336, 2019). "TGF-β signaling is pivotal for tissue development in normal cells and aberrant proliferation and EMT in cancer cells, as a critical modulator of TGF-β signaling, the deregulation of TGFBR2 has the potential to affect a variety of biological processes of prostate cancer cells." (PMID 29699590, 2018). "Methylation silencing of TGFBR2 was found in rat prostate cancers, further studies also proved AR/miRNA-21 or AR/miR-2909 positive feedback loop down-regulated the expression of TGFBR2, leading to attenuation of TGF-β mediated Smad2/3 activation and subsequent tumor-suppressive activity." (PMID 29699590, 2018). "The present study demonstrated that hypoxia could attenuated the expression of TGFBR2 to promote prostate cancer progression via diverse cellular pathways." (PMID 29699590, 2018). "Some evidences in prostate cancer have demonstrated that androgens may downregulate TGFBR2 gene expression through a transcriptional mechanism in which DHT suppresses the binding of the transcription factor Sp1 to the TGFBR2 promoter." (PMID 26091707, 2016). "In addition, other studies in prostate cancer demonstrated that AR may regulate the decrease in TGFBR2 levels through micro-RNA-21." (PMID 26091707, 2016). "While the expression of other prostate cancer EMT markers HAS-3, AHNAK2, TGFBR2, ANXA2, and ANXA3 was higher in DU145 compared with DUTXR (Fig. 1CII–IV)." (PMID 37476073, 2023). "Upregulation of TGFBR2 enables pro-apoptotic activity of TGF-β1 and inhibits the growth of prostate cancer cells through a caspase-1-mediated mechanism, whereas downregulation of this receptor leads to stimulation of malignant transformation." (PMID 31842336, 2019). "Downregulation or loss of TGF-β receptors was observed in about 30% of cases of prostate cancer compared with normal prostate tissues while expressions of TGFBR1 and TGFBR2 were lower in metastatic compared with primary tumors." (PMID 31842336, 2019). "Decreased expression of miR-133b in prostate tumors and bone metastases leads to upregulation of TGFBR1 and TGFBR2, enabling TGF-β signaling, which contributes to the migration and invasion of prostate cancer cells." (PMID 31842336, 2019).
prostate carcinoma (continued). "In conclusion, hypoxic condition in prostate cancer induces the expression of EZH2 and miR-93, which initiates H3K27me3 in TGFBR2 promoter and microRNA-induced silencing of target gene respectively." (PMID 29699590, 2018). "Our data suggest that DZNeP inhibits SNAIL and TGFBR2, two master regulators of EMT in prostate cancer cells." (PMID 21501485, 2011). "Emerging evidence indicates that downregulation of TGFBR2, a pivotal regulator of TGF-β signaling, may contribute to carcinogenesis and progression of prostate cancer (PCa)." (PMID 29699590, 2018). "Transforming growth factor, beta receptor 2 (TGFBR2), Programmed cell death protein 4 (PDCD4), Reversion-inducing cysteine-rich protein with kazal motifs (RECK), p57kip2 and Phosphatase and Tensin Homolog Deleted from Chromosome 10 (PTEN) have been reported as miR-21 targets in prostate cancer." (PMID 28783103, 2017).